HOGA1 (4-hydroxy-2-oxoglutarate aldolase 1)
Description:
Catalyzes the final step in the metabolic pathway of hydroxyproline.
Synonyms: C10orf65; DHDPSL; FLJ37472; DHDPS2; NPL2; HP3
Tractability: PROTAC: its protein half-life has been measured.
Target class: Enzyme; Lyase
Gene: Protein-coding gene on chromosome 10 (97,584,323 to 97,612,802, forward strand). Ensembl gene ENSG00000241935.
Subcellular location: Mitochondrion
Pathways (Reactome):
Metabolism: Glyoxylate metabolism and glycine degradation
Gene Ontology:
Molecular function: (R,S)-4-hydroxy-2-oxoglutarate aldolase activity; protein binding; protein homodimerization activity; (4S)-4-hydroxy-2-oxoglutarate aldolase activity; lyase activity
Biological process: glyoxylate catabolic process; glyoxylate metabolic process; oxalate metabolic process; pyruvate biosynthetic process; trans-4-hydroxy-L-proline catabolic process
Cellular component: mitochondrion; mitochondrial matrix
Genetic constraint (gnomAD): Loss-of-function variants: 30 observed, 35.98 expected, observed/expected ratio (o/e) 0.83, 90% interval 0.62 to 1.13. The upper end of that interval is the gene's LOEUF score, 1.13, which puts it in group 4 of 6, group 1 being the genes least tolerant of losing a copy. Missense variants: 417 observed, 457.5 expected, observed/expected ratio (o/e) 0.91, 90% interval 0.84 to 0.99. Synonymous variants: 161 observed, 183.83 expected, observed/expected ratio (o/e) 0.88, 90% interval 0.77 to 1.
Gene-disease validity (ClinGen):
ClinGen rates the evidence that HOGA1 causes each of these diseases.
primary hyperoxaluria type 3 (autosomal recessive): Definitive. Primary hyperoxaluria type 3 (PH3) is a disorder of glyoxylate metabolism that can be asymptomatic or characterized by oxalate nephrolithiasis.
Homologues: Orthologues: dog HOGA1 (93% identical), pig HOGA1 (93% identical), mouse Hoga1 (88% identical), guinea pig HOGA1 (87% identical), rat Hoga1 (87% identical), rabbit HOGA1 (79% identical), tropical clawed frog hoga1 (67% identical), zebrafish hoga1 (65% identical). Paralogues in human: NPL (24% identical).
Diseases named in the same sentence as HOGA1 in open-access papers:
HOGA1 is named in the same sentence as 27 diseases in open-access papers, as found by Europe PMC text mining. Sharing a sentence is not in itself a finding about the gene and the disease. The quoted sentences say what the papers report.
primary hyperoxaluria (15 papers, 2015 to 2025). A hereditary disorder characterized by excessive oxalate production, leading to hyperoxaluria. "Loss‐of‐function mutations of HOGA1 in humans cause primary hyperoxaluria type 3 (PH3), a rare autosomal recessive disease characterised by excessive production of oxalate and kidney stones." (PMID 40100076, 2025). "Primary hyperoxaluria type 3 (PH3) is a rare autosomal recessive disorder caused by bi-allelic genetic variants in the 4 hydroxy-2 oxoglutarate aldolase (HOGA-1) gene." (PMID 39476025, 2025). "HOGA1 encodes the mitochondrial 4-hydroxy-2-oxoglutarate aldolase, and mutations cause oxalate accumulation in the kidney and primary hyperoxaluria type 3." (PMID 35873461, 2022). "Primary hyperoxalurias (PHs) are rare autosomal recessive diseases of the glyoxylate metabolism; PH1 is caused by mutations in the AGXT gene, PH2 in GRHPR and PH3 in HOGA1." (PMID 35218550, 2022). "Primary hyperoxaluria (PH) is an autosomal recessive disorder of oxalate metabolism caused by pathogenic variants in either of three genes (AGXT, GRHPR or HOGA1)." (PMID 36151119, 2022). "HOGA1 is a useful marker for diagnosing primary hyperoxaluria 3, catalysing the final step of mitochondrial hydroxyproline metabolism from 4‐hydroxy‐2‐oxoglutarate (HOG) to glyoxylate and pyruvate; however, its specific mechanism in RCC remains unclear." (PMID 40100076, 2025). "Primary hyperoxaluria (PH), a rare autosomal recessive disease of oxalate accumulation in the kidneys, is caused by biallelic pathogenic changes in three known genes: AGXT (PH1), GRHPR (PH2) and HOGA1 (PH3)." (PMID 40873808, 2025). "Although a possible mutational hotspot in PH3 gene HOGA1 has been identified in the Chinese population, none of the patients in the RaDaR primary hyperoxaluria cohort were from a Chinese background." (PMID 39081723, 2024). "Disorders of oxalate metabolism were noted on 7 genetic results of primary hyperoxaluria genes (Type 1 AGXT, Type 2 GRHPR, and Type 3 HOGA1) in 7 patients (6%)." (PMID 40126616, 2025). "Dent disease (with inclusion of CLCN5 and OCRL1 genes) and primary hyperoxaluria (PH) (with inclusion of AGXT and HOGA1 genes) were identified with high frequency." (PMID 35612621, 2022). "Definitive diagnosis of primary hyperoxaluria (PH) currently utilizes sequential Sanger sequencing of the AGXT, GRPHR, and HOGA1 genes but efficacy is unproven." (PMID 25629080, 2015).
Hyperoxaluria (4 papers, 2022 to 2024). Increased excretion of oxalates in the urine. "Hyperoxaluria-related mutations were detected in nine patients (three AGXT defects, three GRHPR defects, and three HOGA1 defects), and calcium oxalate stones were found in eight of these patients as a result of stone sample evaluation." (PMID 37144129, 2023). "Both hyperoxaluric and non-hyperoxaluric patients were screened for sequence variations in known and candidate genes implicated in hyperoxaluria (AGXT, GRHPR, HOGA1, SLC26A1, SLC26A6, SLC26A7) by targeted next generation sequencing (tNGS)." (PMID 37270618, 2023). "The exome analysis revealed that other disease-causing mutations related to hyperoxaluria were also present in AGXT (PH1), and HOGA1 (PH3)." (PMID 36619171, 2022). "To evaluate the contribution of genetic factors in the development of hyperoxaluria after bariatric surgery, we conducted tNGS to detect variations within genes known to cause monogenic hyperoxaluria and Ca-Ox-NL (AGXT, GRHPR, HOGA1; SLC26A1) as well as the candidate genes SLC26A6 and SLC26A7." (PMID 37270618, 2023). "Moreover, three genes, AGXT, HOGA1 and GRHPR with Novel variants known to cause hyperoxaluria were found frequently in the study cohort." (PMID 36619171, 2022).
kidney stones (2 papers, 2021 to 2025). "The third patient (#4) suffered recurrent nephrolithiasis from infancy until adulthood and eventually was found to be compound heterozygote with two pathogenic variants in HOGA1 on whole genome sequencing." (PMID 39476025, 2025).
Insulin resistance (1 paper, 2022). Increased resistance towards insulin, that is, diminished effectiveness of insulin in reducing blood glucose levels. "Hoga1 ASO treatment ameliorated the clinical indexes of insulin resistance including glucose, insulin, and homeostatic model assessment of insulin resistance (HOMA-IR) levels in HFD-induced mice." (PMID 36035184, 2022). "Obesity-induced insulin resistance has been reported; therefore, T2D parameters were assessed in HFD-induced mice treated with Hoga1 ASO." (PMID 36035184, 2022).
kidney cancer (1 paper, 2025). Primary or metastatic malignant neoplasm involving the kidney. "Our previous studies showed that HOGA1 was downregulated in expression in kidney cancer." (PMID 40100076, 2025).
Obesity (1 paper, 2022). Accumulation of substantial excess body fat. "Taken together, HOGA1 is a potential causal gene for obesity as it plays a role in excess body fat development." (PMID 36035184, 2022). "The anti-obesity effect of Hoga1-targeted ASO was corroborated and extended in diet-induced obese mice." (PMID 36035184, 2022). "Functional analyses employing cell- and animal model-based approaches were performed to gain insights into the functional relevance of Hoga1 in obesity." (PMID 36035184, 2022). "Therefore, targeting HOGA1 could be a potential therapeutic target for obesity." (PMID 36035184, 2022).
pancreatic cancer (1 paper, 2022). "Taken together, these results indicated that HOGA1 loss in pancreatic cancer promoted cancer progress through activating LARP7-CDK1 pathway." (PMID 36434634, 2022). "HOGA1 functions like a tumor suppressor and HOGA1 decreased notably in pancreatic cancer, indicating the loss of HOGA1 might affect PDAC progression." (PMID 36434634, 2022). "To investigate the role of HOGA1 in the development of pancreatic cancer, we constructed both HOGA1 overexpressed and HOGA1 knocked down PANC-1 and BxPC-3 cell lines and performed further analysis." (PMID 36434634, 2022). "We found that HOGA1 (4-hydroxy-2-oxoglutarate aldolase, mitochondrial) was downregulated by more than 80% in pancreatic cancer tumor tissues compared with non-tumor tissues in proteomic results (Student’s t test, P < 1.0E−4, FC = 0.14), and western blotting of 12 pairs of pancreatic cancer tissues." (PMID 36434634, 2022). "Therefore, the decreased expression of HOGA1 might be a diagnostic indicator of PDAC, and inhibiting LARP7, which collaborated with HOGA1, would provide another feasible strategy for suppressing pancreatic cancer development in clinic." (PMID 36434634, 2022).
renal carcinoma (1 paper, 2025). A carcinoma arising from the epithelium of the renal parenchyma or the renal pelvis. "Furthermore, in vitro and in vivo assays demonstrated that HOGA1 significantly inhibited the proliferation, invasion and migration of renal carcinoma cells via the Wnt/β‐catenin–c‐Myc/CyclinD1 axis, probably via regulating the level of HOG." (PMID 40100076, 2025). "Consequently, HOGA1 may play a significant role in various diseases, particularly those related to the kidneys, including renal cancer." (PMID 40100076, 2025). "Additionally, we compared HOGA1 expression with tumour grade in 11 pairs of clinical renal cancer samples and found that six pairs were Grade I, while the remaining five were Grade II, further suggesting that higher tumour grade is associated with lower HOGA1 expression." (PMID 40100076, 2025). "This suggests that the role of HOGA1 and HOG in renal cancer may be more extensive and has yet to be fully explored." (PMID 40100076, 2025). "Therefore, it may be meaningful to explore the regulation of HOGA1 and HOG on hydroxyproline or glyoxylate metabolism in renal cancer in the future." (PMID 40100076, 2025).
urolithiasis (1 paper, 2025). Stone(s) within the urinary tract. "Our heterozygote patient underwent whole genome sequencing looking for a second genetic variant to exclude the possibility of compound heterozygosity or a deletion in HOGA1 or other genetic cause for urolithiasis." (PMID 39476025, 2025).
cancer (2 papers, 2022 to 2025). A tumor composed of atypical neoplastic, often pleomorphic cells that invade other tissues. "Furthermore, a proteogenomic study on pancreatic ductal adenocarcinoma cancer showed that loss of HOGA1 promoted the proliferation of cancer cells by regulating the cell cycle." (PMID 40100076, 2025). "The Wnt/β‐catenin signalling pathway, known to be involved in cell proliferation and metastasis in various cancers, was enriched significantly by Hoga1‐coexpressed genes." (PMID 40100076, 2025). "Overexpression of HOGA1 did not further inhibit cancer cell proliferation, invasion and migration in the β‐catenin knocked‐down ccRCC cell lines." (PMID 40100076, 2025).
tumor (2 papers, 2022 to 2025). "The results showed that HOGA1 was decreased significantly in tumour tissues, with this low expression associated with a poor prognosis in patients with ccRCC." (PMID 40100076, 2025). "Experiments utilizing both in vivo and in vitro assay proved that loss of HOGA1 promoted the tumor growth via activating LARP7-CDK1 pathway." (PMID 36434634, 2022). "Targeting LARP7 was able to intercept the tumor-promoting effect of HOGA1 loss and avoid affecting glyoxylate metabolism." (PMID 36434634, 2022). "Moreover, low levels of HOGA1 expression were associated with significantly worse overall survival, with HOGA1 expression decreasing with increasing tumour grade." (PMID 40100076, 2025). "Finally, we found that loss of HOGA1 promoted the tumor growth via activating LARP7-CDK1 pathway." (PMID 36434634, 2022). "In conclusion, this study demonstrates that HOGA1 has a tumour suppressor role by inhibiting the Wnt/β‐catenin signalling pathway." (PMID 40100076, 2025). "We showed that the proliferation rate in the HOGA1‐OE group was significantly lower than that in the control group, while the subcutaneous tumour weight of the HOGA1‐OE group decreased significantly." (PMID 40100076, 2025). "To further confirm the role of HOGA1 in ccRCC development in vivo, we established a tumour xenograft model in NOD SCID mice by subcutaneously injecting control or 786‐O cells with stable overexpression of HOGA1." (PMID 40100076, 2025). "Staining of the cell proliferation marker Ki67 also showed a sharp decrease along with an increase in HOGA1 staining in tumour tissues." (PMID 40100076, 2025). "Further study showed that HOGA1 has a tumour suppressor role by inhibiting the Wnt/β‐catenin signalling pathway via regulating the level of its substrate HOG." (PMID 40100076, 2025). "Here, we showed that HOGA1, which was previously known as a mitochondrial protein and involved in metabolism of hydroxyproline to glyoxylate, contributed to tumor progression through its signaling role." (PMID 36434634, 2022). "HOGA1 was reduced significantly in ccRCC, suggesting that it suppressed tumour gene function." (PMID 40100076, 2025). "In summary, our current findings demonstrate that HOGA1 functions as a tumour suppressor in ccRCC, which can inhibit the Wnt/β‐catenin–c‐Myc/CyclinD1 axis by regulating the level of HOG, presenting a novel therapeutic strategy focusing on the regulation of hydroxyproline metabolism for ccRCC." (PMID 40100076, 2025). "To determine whether the metabolic enzymatic activity of HOGA1 is important for the expansion of tumor cells, we treated PANC-1 and BxPC-3 cells with hydroxyproline and glyoxylate, respectively, and found the neither of them affected the cell proliferation." (PMID 36434634, 2022). "In addition, we noted that loss of HOGA1 expression promoted the xenograft growth of PANC-1 cells, whereas knockdown of LARP7 abrogated the effect of HOGA1 and delayed the xenograft growth of tumor cells." (PMID 36434634, 2022). "Together with the observations that HOGA1 not only expressed in mitochondrial, but also located in cytosol, these results suggested that the tumor suppressor role of HOGA1 was not due to its metabolic activity." (PMID 36434634, 2022).
HOGA1 also shares sentences with these, for which no sentence is quoted: primary hyperoxaluria type 3 (5 papers); Dent disease (2); primary hyperoxaluria type 1 (2); cystinuria (1); distal renal tubular acidosis (1); genetic disorders (1); Hypercalciuria (1); hypophosphatemic rickets (1); Kabuki syndrome (1); osteopetrosis (1); pancreatitis (1); primary hyperoxaluria type 2 (1); renal cell carcinoma (1); renal tubular acidosis (1); sarcopenia (1); xanthinuria type I (1).